INS (insulin)
Diseases named in the same sentence as INS in open-access papers (continued):
Sharing a sentence is not in itself a finding about the gene and the disease.
neurodegenerative disease (210 papers, 2007 to 2026). A disorder of the central nervous system characterized by gradual and progressive loss of neural tissue and neurologic function. "Aside from their obvious metabolic sequelae, insulin resistance in the central nervous system and cerebral glucose metabolism have also been associated with neurodegenerative diseases, despite brain glucose uptake being insulin-independent." (PMID 38177108, 2024). "Hyperactivation of phosphatase PP2A in the brain, causing central IR and an imbalance in the regulatory effects of insulin and other neurohormones, is closely associated with neurodegenerative diseases, including AD and Parkinson’s disease." (PMID 36834685, 2023). "Since deregulated neuronal insulin signaling leading to neuronal insulin resistance has been linked to many neurodegenerative diseases, the potential role of PHLPP phosphatase is impending." (PMID 36376971, 2022). "Nonetheless, aberrant insulin signaling it is increasingly recognized in its association with neurodegenerative diseases of the CNS." (PMID 33925119, 2021). "Alterations of brain insulin signaling have been associated with a higher risk of developing age-related cognitive decline and neurodegenerative diseases." (PMID 32733190, 2020). "Previous evidence has shown that the impairment of brain insulin signaling is associated with progressive neurodegenerative diseases such as AD and neuronal death." (PMID 32138327, 2020). "Disturbances in insulin signaling have been implicated in several neurodegenerative diseases including AD, PD, and HD." (PMID 30072954, 2018). "Insulin signaling in the CNS is important because of the conspicuous relationship between dysfunctional insulin signaling and disturbed learning and memory in neurodegenerative diseases, such as AD." (PMID 29973864, 2018). "Although the precise role of insulin in the brain is not fully understood, impaired insulin signaling is a hallmark of brain aging and many neurodegenerative diseases." (PMID 25889938, 2015). "Additionally, fructose-induced alterations in insulin signaling in the brain are associated with increased risk for neurodegenerative diseases." (PMID 40297675, 2025). "Therefore, it is easy to guess that defects in this process are widely associated with many diseases, including neurodegenerative diseases associated with brain insulin resistance, such as AD." (PMID 35741464, 2022). "Overall, our study suggests that modulation of the insulin/IGF signalling pathway could be an effective therapeutic intervention against hexanucleotide repeat extension associated with C9orf72 neurodegenerative diseases, with InR being a genetic modifier." (PMID 33739284, 2021). "While the underlying mechanisms that promote sporadic neurodegenerative disease pathogenesis remain elusive, mounting evidence point to the associations between the disruption of metabolites processing in insulin impairment and neurodegenerative conditions such as AD." (PMID 31892368, 2019). "Defects in insulin mechanisms are also associated with neurodegenerative diseases." (PMID 27898058, 2016). "As there are many functions of insulin, the impairment of insulin function leads to multiple deficits in both the brain and the peripheral tissues that could be associated with other neurodegenerative diseases." (PMID 26075247, 2015). "Whilst GLP-1 receptor activation can exert multiple direct neuroprotective effects, the protective influence of GLP-1 receptor agonists may occur indirectly through the restoration of the dysfunctional insulin signaling associated with neurodegenerative disease." (PMID 36258018, 2023). "Considering that lower cerebral levels of insulin have been associated with neurodegenerative diseases such as Alzheimer’s, a potential adaptive significance of insulin expression in NGFC could be a modulation of neighboring neuronal circuits involved in learning and memory." (PMID 37047558, 2023).
neurodegenerative disease (continued). "In the remainder of this manuscript, we aimed to overview the data yielded mainly by more recent studies concerning specifically the actions of insulin synthesized in various brain regions and how their impairment may be associated with some neurodegenerative diseases." (PMID 37047558, 2023). "Apart from controlling blood glucose, insulin has the general physiological profile of a growth factor (insulin modulates neuronal development, synaptic transmission, and neuroprotection, whereas insulin resistance impairs learning and memory and increases neurodegenerative disease risk)." (PMID 36012569, 2022). "Additionally, while not discussed in more detail, it is important to note that there is likely at least some contribution of impaired insulin transport into the brain in response to a HFD and during neurodegenerative diseases associated with brain insulin resistance." (PMID 33845179, 2021). "In addition to the impairment of insulin signaling, the brain/neuron-specific insulin-receptor KO mice exhibited a substantial increase in the phosphorylation of the microtubule-associated protein tau, a hallmark of neurodegenerative diseases." (PMID 26075247, 2015). "This disruption impacts insulin resistance and adipocytokine signaling pathways, thereby promoting the development of neurodegenerative diseases." (PMID 41465406, 2025). "Chronic inflammation also leads to severe alterations in insulin signaling and extensive protein post-translational modification, which are considered hallmarks of both chronic metabolic disorders and neurodegenerative diseases." (PMID 41129928, 2025). "This study not only elucidates the mechanism by which insulin increases GSH levels in the brain but also suggests a plausible strategy for the clinical application of intranasal insulin administration in the treatment of neurodegenerative diseases." (PMID 40699683, 2025). "Although little is known about the role of insulin signaling on the activity of NVU cells, impairment of insulin signaling has been identified as a mechanism in neurodegenerative diseases." (PMID 39456952, 2024). "Data from several human and animal studies have shown that the dysregulation of insulin function contributes to the development of neurodegenerative diseases." (PMID 38255204, 2024). "The efficacy of these interventions in improving insulin sensitivity and cognitive function underscores the potential for personalized approaches to prevent and treat metabolic and neurodegenerative diseases." (PMID 39659426, 2024). "Insulin can affect glial activation, participating in neuroinflammation, which is an inextricable pathological process with IR in neurodegenerative diseases." (PMID 38952394, 2024). "Similar effects were observed in mammalian cells, suggesting a therapeutic potential in targeting insulin signaling pathways for C9orf72-related neurodegenerative diseases." (PMID 38791099, 2024). "Studies done both in humans and in experimental animals have shown that dysregulation of insulin function promotes ageing and the development of neurodegenerative diseases." (PMID 39170185, 2024). "The comprehensive beneficial effects of exercise suggest its potential as a crucial approach for improving insulin resistance by targeting mitochondrial quality and ultimately mitigating neurodegenerative diseases." (PMID 38818523, 2024). "Increasing insulin levels, enhancing insulin sensitivity, and regulating blood glucose levels can ameliorate neurodegenerative diseases." (PMID 38818523, 2024). "The focus was on regulating insulin resistance through exercise and providing practical ideas and suggestions for future research focused on exercise-induced insulin sensitivity in the context of neurodegenerative diseases." (PMID 38818523, 2024). "This review elucidates the relatively complex and critical molecular mechanisms involved in insulin resistance, neurodegenerative diseases, and the exercise-induced enhancement of insulin sensitivity." (PMID 38818523, 2024).
neurodegenerative disease (continued). "That is, functional insulin and downstream elements in insulin signaling pathways are required in neurodegenerative diseases." (PMID 38952394, 2024). "Overall, intranasal and topical insulin presents a promising treatment strategy for neurodegenerative diseases, though further research is required to validate its efficacy." (PMID 39458902, 2024). "Previous studies on neurodegenerative diseases, mainly AD, have identified impaired insulin signaling as a crucial factor in AD." (PMID 37511207, 2023). "While AD is at the forefront of research into the use of insulin in neurodegenerative disease, there is increasing attention being paid to the role of insulin signaling in PD." (PMID 36258018, 2023). "Currently, an increasing number of basic experiments and clinical studies have demonstrated that the modulation of insulin signaling has a considerable role in treating neurodegenerative disease." (PMID 37063831, 2023). "Multiple in vitro and in vivo experiments have shown a regulatory role for insulin or IGF signaling pathways in neurodegenerative disease models, which has been translated into clinical trials with limited success." (PMID 38132161, 2023). "The most studied amyloids are those directly involved in neurodegenerative diseases, while others, such as those formed by insulin, are surprisingly far less studied." (PMID 36674821, 2023). "The importance of insulin in the metabolism of glucose in the brain has gained attention in the last few decades through research into the pathogenesis of neurodegenerative diseases such as AD and PD." (PMID 36979662, 2023). "IR, characterized by a diminished response to insulin from target tissues, plays an important role in neurodegenerative diseases that affect neuronal metabolism." (PMID 37904099, 2023). "Empagliflozin’s insulin-reducing capability is of great importance for neurodegenerative diseases, as chronically elevated insulin levels downregulate autophagy and inhibit clearance of abnormal proteins." (PMID 36359767, 2022). "To find a possible correlation between the insulin resistance of neurons and neurodegenerative disease, we performed Western blotting analysis for the key phosphoproteins involved in AMPK and integrin pathways in the brains of 5xFAD mice." (PMID 35055191, 2022). "Insulin signalling is critical for neuronal function, where disruptions to signalling can underpin the pathologies seen in neurodegenerative diseases such as AD." (PMID 36555450, 2022). "It is therefore reasonable to suggest that restoring insulin signalling via administering insulin is one strategy to prevent neurodegenerative diseases such as AD." (PMID 36555450, 2022). "Therapy targeting the insulin-signaling pathway is viewed as a promising approach for treating neurodegenerative diseases." (PMID 36162508, 2022). "Summary of the studies highlighting a link between BVR-A alterations and insulin signaling-related pathways in neurodegenerative diseases." (PMID 35628384, 2022). "Most of these research works mainly focus on AD pathology, AD being a neurodegenerative disease extensively studied to understand the role of brain insulin resistance on its pathogenesis." (PMID 35628384, 2022). "Ramalingam and Kim have shown the importance of the PI3K/AKT pathway of insulin signaling, not only for neuronal survival in neurodegenerative diseases, but also for α-syn accumulation." (PMID 35454152, 2022). "Based on this knowledge, the idea of using insulin as a potential therapeutic agent in neurodegenerative diseases has been developed." (PMID 35741464, 2022). "The downregulation of “cAMP signaling”, “insulin secretion”, and neuronal function-related pathways in “T2D and AD” highlights similarities of the two degenerative diseases." (PMID 36345338, 2022). "Nasal insulin has also been tested in other neurodegenerative diseases, showing for example improved clinical outcome in PD severity." (PMID 35087428, 2021).
neurodegenerative disease (continued). "In animal models of neurodegenerative diseases, exogenous insulin, administered intranasally or topically, demonstrates neuroprotective effects such as promoting neuronal survival, enhancing mitochondrial function, and reducing neuro-inflammation." (PMID 33925119, 2021). "In clinical trials, the intranasal administration of insulin to patients with Alzheimer’s and other neurodegenerative diseases was shown to improve the cognitive functions (see, for example,)." (PMID 34769198, 2021). "The beneficial actions of GLP-1 go far beyond insulin secretion and appetite, and include cardiovascular benefits and possibly also beneficial effects in neurodegenerative diseases." (PMID 34168620, 2021). "Neuroprotective effects of exogenous insulin administration in experimental models of neurodegenerative diseases." (PMID 33925119, 2021). "Human and animal studies have shown that dysregulation of insulin function contributes to aging and to the development of neurodegenerative diseases." (PMID 35087428, 2021). "Emerging data suggests that insulin can improve neuronal survival or recovery after trauma or during neurodegenerative diseases." (PMID 33100956, 2020). "The role of both insulin and sphingolipids is well documented in AD and other neurodegenerative diseases." (PMID 32192109, 2020). "Picone and collaborators developed PVP nanogels covalently attached insulin for intranasal administration demonstrating an increase in the brain insulin delivery and potential use for neurodegenerative diseases." (PMID 33076231, 2020). "Conjugates introduced to insulin with suitable linkers have the potential to be used for the treatment of neurodegenerative diseases through nasal administration." (PMID 33171799, 2020). "Functional enrichment analysis also shows that the KEGG pathways were focused on pentose phosphate pathway, endocytosis and insulin resistance, oxidative phosphorylation and neurodegenerative diseases." (PMID 31178714, 2019). "In contrast, studies done in APP/PS1 mice show that insulin sensitivity improves autophagy in neurodegenerative disease models." (PMID 31427921, 2019). "RSV antioxidant treatments are effective at increasing insulin sensitivity, developing mitochondrial functions, and providing protection against cardiovascular and neurodegenerative diseases." (PMID 29887910, 2018). "In conclusion, supporting mitochaperone function in metabolic and neurodegenerative diseases can improve brain insulin signaling as well as metabolism and represents a novel strategy to improve neuronal health and metabolism contributing to healthy aging." (PMID 29755410, 2018). "Reduced insulin signaling, however, can improve symptoms of neurodegenerative diseases in different model organisms and protect against age-associated decline in neuronal function extending lifespan." (PMID 28902870, 2017). "In rodents, reduced insulin/IGF1 signaling slows aging and therefore prevents development of neurodegenerative diseases but normal aging is associated with declining levels of IGF1 and administration of insulin can improve cognitive function in AD patients." (PMID 26932723, 2016). "Converging evidence from animal models has greatly furthered our understanding of the role that insulin signaling plays in cognition and neurodegenerative disease." (PMID 30202553, 2016). "Along with more recent data linking brain insulin/IGF-1 function to the etiology of a number of neurodegenerative diseases will, undoubtedly, translate into more clinically oriented avenues of research in the near future." (PMID 26417600, 2015). "The disruption of insulin signalling and glucose transport in neurons can contribute to the progression of neurodegenerative diseases such as AD." (PMID 26693205, 2015).
neurodegenerative disease (continued). "The accumulating evidence that reduced glucose utilization and deficient energy metabolism occur early in the course of disease, suggests a role for impaired insulin signaling in the pathogenesis of neurodegenerative diseases." (PMID 26136647, 2015). "Insulin signaling has a direct role in the development of neurodegenerative diseases, and insulin administration improves memory." (PMID 25356910, 2014). "The brain is a highly insulin sensitive organ and T2DM is known as a risk factor for many neurodegenerative diseases, including AD and PD in which the repositioning of Ex-4 is already being assessed as a new clinical treatment strategy." (PMID 22384126, 2012). "In summary, evidence shows that insulin and insulin-sensitizing agents can be useful in the treatment of neurodegenerative diseases, mitochondria being one of the key targets." (PMID 27713238, 2009). "As evidenced by Naseem’s suppression of human insulin fibrillation, esculin’s anti-amyloidogenic capabilities may make it a promising therapy option for neurodegenerative diseases in the near future." (PMID 40810072, 2025). "Here, we provide a scientific perspective regarding the significance of exercise-reversed insulin resistance in neurodegenerative diseases that will ultimately contribute to the prevention and treatment of neurodegenerative diseases in an increasingly older population." (PMID 38818523, 2024). "However, an increasing number of studies have observed that insulin signaling elicits abnormal changes involved in the occurrence and development of multiple neurodegenerative diseases." (PMID 38818523, 2024). "A chronic imbalance of insulin metabolism, which manifests as type 2 diabetes, is a potential risk for the most common non-heritable neurodegenerative diseases." (PMID 37512524, 2023). "However, insulin regulates brain functions and neurodegenerative diseases across different regions and cross-talk with other tissues, such as liver, to fine-tune whole body function." (PMID 36942499, 2023). "In this review, we focus on how GLP-1 receptor agonists, insulin and other incretin mimetics exert multiple neuroprotective effects and could provide an effective new therapeutic strategy for neurodegenerative diseases." (PMID 36258018, 2023). "Therefore, understanding the underlying mechanisms of insulin and IGF-1 in the brain is essential for the development of new treatments for neurodegenerative diseases." (PMID 37511207, 2023). "In relation to the protective effect of insulin on the brain, neurodegenerative diseases, such as MS, may arise because of decreased central insulin." (PMID 35989823, 2022). "It is conceivable that an improvement in insulin signaling could overcome dysfunction in the brain in both metabolic and neurodegenerative diseases." (PMID 35741464, 2022). "Defective insulin signaling plays a role in brain dysfunction, such as neurodegenerative disease." (PMID 35741464, 2022). "The association of this dysregulated miRNA with cognitive function and metabolic dysfunction could be mediated through its role in regulating gene sets related with neurodegenerative diseases and insulin signaling." (PMID 33911114, 2021). "Restoring insulin signaling in the brain may provide a therapeutic benefit in neurodegenerative diseases." (PMID 33925119, 2021). "Insulin’s role in stimulating glycogen formation in astrocytes is essential in maintaining stores sufficient to support the metabolic demands of the stressed and unstressed neurons in neurodegenerative diseases." (PMID 33925119, 2021). "However, a growing number of pre-clinical and clinical studies have demonstrated the potential of modulating insulin signaling in the treatment of neurodegenerative diseases." (PMID 33925119, 2021). "Targeting insulin metabolic-related metabolic manifestations might be an effective strategy to treat this currently incurable neurodegenerative disease." (PMID 33291072, 2020).